BTG3 (BTG anti-proliferation factor 3)
Description:
Overexpression impairs serum-induced cell cycle progression from the G0/G1 to S phase.
Synonyms: ANA; TOB5; tob55; APRO4; ANA/BTG3; TOFA
Tractability: PROTAC: ubiquitination databases record sites on it.
Gene: Protein-coding gene on chromosome 21 (17,593,650 to 17,613,014, reverse strand). Ensembl gene ENSG00000154640.
Gene Ontology:
Molecular function: protein binding
Biological process: negative regulation of mitotic cell cycle; negative regulation of cell population proliferation
Cellular component: cytoplasm; nucleus
Genetic constraint (gnomAD): Loss-of-function variants: 4 observed, 26.95 expected, observed/expected ratio (o/e) 0.15, 90% interval 0.072 to 0.34. The upper end of that interval is the gene's LOEUF score, 0.34, which puts it in group 1 of 6, group 1 being the genes least tolerant of losing a copy. Missense variants: 201 observed, 323.11 expected, observed/expected ratio (o/e) 0.62, 90% interval 0.55 to 0.7. Synonymous variants: 107 observed, 106.2 expected, observed/expected ratio (o/e) 1.01, 90% interval 0.86 to 1.18.
Homologues: Orthologues: chimpanzee BTG3 (99% identical), macaque BTG3 (99% identical), dog BTG3 (97% identical), pig BTG3 (97% identical), rabbit BTG3 (95% identical), guinea pig BTG3 (94% identical), mouse Btg3 (94% identical), rat Btg3 (92% identical), tropical clawed frog btg3 (50% identical), zebrafish btg3 (47% identical). Paralogues in human: BTG4 (41% identical), BTG1 (22% identical), BTG2 (20% identical).
Diseases named in the same sentence as BTG3 in open-access papers:
BTG3 is named in the same sentence as 68 diseases in open-access papers, as found by Europe PMC text mining. Sharing a sentence is not in itself a finding about the gene and the disease. The quoted sentences say what the papers report.
prostate carcinoma (10 papers, 2013 to 2024). A carcinoma that arises from epithelial cells of the prostate gland. "Btg3-deficient (Btg3–/–) mice display a higher incidence of lung tumors, and the downregulation of BTG3 has been observed in renal, breast, and prostate cancers, suggesting that BTG3 may play a role in suppressing tumorigenesis." (PMID 38714880, 2024). "After the exposure to 5-Aza, CRC cells showed the attenuated promoter methylation and strengthened BTG3 mRNA expression, which was reported in gastric, breast, renal and prostate cancer cells." (PMID 28407690, 2017). "We treated cells with 5-Aza and observed the restoration of BTG3 mRNA expression in gastric cancer cells, in line with the reports about breast, renal and prostate cancer cells." (PMID 25904053, 2015). "To determine the clinical relevance of the BTG3-AKT axis, we performed IHC staining on paraffin-embedded sections of clinical prostate cancer specimens to compare the levels of BTG3 and phospho-AKT (pT308)." (PMID 25569101, 2015). "Activation of HAT activity by GEN was involved in the re-expression of BTG3 (B-Cell translocation gene 3) in prostate cancer cell lines." (PMID 25322458, 2014). "Methylation-mediated down-regulation of BTG3 was also documented in renal and prostate cancer cells." (PMID 23657964, 2013). "Interestingly, it was found that the expression of VEGFA is negatively correlated with the copy number of BTG3 in prostate cancer." (PMID 33311481, 2020). "Similarly, overexpression of BTG3 in the prostate cancer cell line DU145 dampened serum-induced AKT activation, suggesting that this is not a cell-type-specific effect." (PMID 25569101, 2015). "BTG3 downregulation has been observed in many cancers, including renal, breast, and prostate cancer, but its role in non-melanoma skin cancer is unclear." (PMID 38714880, 2024). "The activation of a tumor suppressor gene, B-cell translocation gene 3 (BTG3), which is downregulated in cancer due to its hypermethylation, was initiated by genistein through the demethylation of CpG island in the promoter of the gene in prostate cancer cells." (PMID 30823649, 2019).
colorectal cancer (8 papers, 2017 to 2024). A primary or metastatic malignant neoplasm that affects the colon or rectum. "The overexpression of CA3-AS1 suppressed the proliferation, invasion, and metastatic capabilities of both gastric cancer and colorectal cancer cells through modulation of the miR-93/BTG3/PTEN axis." (PMID 38279317, 2024). "BTG3 overexpression suppressed the proliferation and invasion of epithelial ovarian and colorectal cancer cells by weakening Akt/GSK3β/β-catenin signaling." (PMID 36186486, 2022). "In our previous work, BTG3 overexpression was demonstrated to reverse the aggressive phenotypes of gastric and colorectal cancer cells." (PMID 36186486, 2022). "BTG3 was also reported to induce the differentiation of gastric and colorectal cancer cells, evidenced by a higher level of alkaline phosphatase." (PMID 36186486, 2022). "A body of evidence identified BTG3 as a direct downstream target of miR-519c-3p and miR-20b-5p, which promoted proliferation and migration in hepatocellular carcinoma and colorectal cancer cells, respectively." (PMID 36186486, 2022). "Further, it has been revealed that B-cell translocation gene (BTG3) knockdown is related to over-expression of multiple genes including YWHAB in colorectal cancer." (PMID 31387239, 2019). "B-cell translocation gene 3 (BTG3) has been identified as a candidate driver gene for various cancers, but its specific role in colorectal cancer (CRC) is poorly understood." (PMID 29270670, 2018). "We aimed to investigate the relationship between expression of BTG3 and clinicopathological features and prognosis, as well as to explore the effects and the role of a possible BTG3 molecular mechanism on aggressive colorectal cancer behavior." (PMID 29270670, 2018). "BTG3 is known as a tumor suppressor in many kinds of cancers, BTG3 knockdown could relieve G2 phase arrest in colorectal cancer cells." (PMID 38777825, 2024). "BTG3 was downregulated in colorectal cancer tissues and positively correlated with pathological classification (p = 0.037), depth of invasion (p = 0.016), distant metastasis (p = 0.024), TNM stage (p = 0.007), and overall survival (OS) and disease-free survival (DFS)." (PMID 29270670, 2018). "BTG3 overexpression might reverse the aggressive phenotypes and be employed as a potential target for gene therapy of colorectal cancer." (PMID 28407690, 2017). "BTG3 knockdown might strengthen the aggressive colorectal cancer behavior." (PMID 29270670, 2018). "BTG3 expression was statistically higher in colorectal cancer and adenoma than adjacent non-neoplastic mucosa (p<0.05)." (PMID 28407690, 2017).
hepatocellular carcinoma (8 papers, 2013 to 2022). A malignant tumor that arises from hepatocytes. "Increased levels of miR-519c-3p were found to promote tumor growth and proliferation in hepatocellular carcinoma cells, by targeting the BTG3 gene." (PMID 34315420, 2021). "Ectopic BTG3 expression reversed the aggressive behaviors of gastric cancer and hepatocellular cancer cells in vitro, and inhibited the tumor growth of lung and gastric cancers in vivo." (PMID 28407690, 2017). "Reportedly, BTG3 expression was inversely correlated with differentiation, lymph node metastasis, or distant metastasis of esophageal, gastric and hepatocellular cancers." (PMID 28407690, 2017). "In contrast, BTG3 is reported at a low expression level in some cancer tissues or cells, such as lung cancer and hepatocellular carcinoma." (PMID 28922388, 2017). "The down- regulated expression of BTG3 is documented in ovarian, lung, prostate or renal, hepatocellular cancer tissues or cells, and its expression is restored by the treatment with genistein and 5-aza-2′- deoxycytidine." (PMID 25904053, 2015). "However, a recent study reported that miR-519c could worsen the prognosis of hepatocellular carcinoma (HCC) by negatively regulating the expression of BTG antiproliferation factor 3 (BTG3) which could promote growth and metastasis of HCC." (PMID 31885571, 2019). "BTG3 (B-cell translocation gene 3) has been identified as a tumor suppressor and hypermethylation contributes to its down-regulation in some tumors, but its role in hepatocellular carcinoma (HCC) remain unknown." (PMID 24147003, 2013).
lung carcinoma (8 papers, 2013 to 2025). "In addition, BTG3 expression was found to be negatively associated with the tumor size of lung cancer." (PMID 36186486, 2022). "Cox’s risk proportional regression model indicated that T staging, lymph node status and BTG3 expression were independent prognostic factors for lung cancer patients (p < 0.05)." (PMID 36186486, 2022). "Reportedly, BTG3 expression was negatively correlated with lymph node metastasis of lung cancer, distant metastasis of gastric and hepatocellular cancers." (PMID 25904053, 2015). "Exogenous BTG3 protein suppresses the levels of matrix metalloproteinase-2 and plasminogen activator inhibitor-1 expression in lung cancer cells." (PMID 23657964, 2013). "Additionally, miR-106b-5p and miR-1290 suppress pro-apoptotic genes such as BTG3, allowing lung cancer cells to evade programmed cell death." (PMID 40149278, 2025). "BTG3 methylation was higher in lung cancer than in normal tissues (p < 0.05)." (PMID 36186486, 2022). "In Xiantao, BTG3 expression was lower in lung cancer than in normal tissues (p < 0.05)." (PMID 36186486, 2022). "Ectopic BTG3 expression decreased proliferation, invasion and induced G1/S cycle arrest of HCC cells in vitro, and inhibited the growth of lung cancer in vivo." (PMID 25904053, 2015). "Exogenous BTG3 overexpression inhibits the expression levels of matrix metalloproteinase (MMP)-2 and plasminogen activator inhibitor-1 in lung cancer cells." (PMID 25904053, 2015). "Exogenous BTG3 protein suppresses the levels of MMP-2 and PAI-1 expression in lung cancer cells." (PMID 28407690, 2017). "On the other hand, analysis of the same datasets did not support a relation of the BTG3/HIF1A ratios with patient survival in prostate and lung cancers, but showed a marginal effect in pancreatic cancer, consistent with our result that BTG3 did not have an obvious impact on HIF1A RNA expression." (PMID 33311481, 2020).
breast carcinoma (7 papers, 2013 to 2022). "In summary, BTG3 mRNA might underlie the molecular mechanisms of the histogenesis of gastric, lung, and breast cancers." (PMID 36186486, 2022). "A higher BTG3 mRNA expression was seen in invasive ductal than lobular carcinomas and negatively correlated with N staging and favorable molecular subtypes (Luminal-type), suggesting that BTG3 might be involved in the progression of breast cancer, and underlay the mechanisms of molecular subtyping." (PMID 36186486, 2022). "According to Xiantao and UALCAN databases, we found that BTG3 expression was lower in breast cancer than in normal tissues (p < 0.05)." (PMID 36186486, 2022). "BTG3 methylation was higher in breast cancer than normal tissues (p < 0.05), N3 than N0, Luminal and Her2+ than TNBC, Her2+ than Luminal cancer patients by UALCAN (p < 0.05)." (PMID 36186486, 2022). "The correlation between BTG3 mRNA expression and clinicopathological characteristics of breast cancer." (PMID 36186486, 2022). "For BTG3, except decreased in breast cancer tissues, consistent with previous report, the vast majority of cancers showed an increased mRNA expression in our study." (PMID 28922388, 2017). "As a member of the anti-proliferative gene family, over-expression of BTG3 also inhibits cell proliferation in breast cancer." (PMID 24147003, 2013). "Furthermore, when incubated with the nonaggressive breast cancer cells T47D, the medium conditioned by BTG3-depleted cells promoted cell scattering, a hallmark of malignant progression." (PMID 33311481, 2020). "Down-regulated BTG3 expression was observed in lung and breast cancers, compared with normal tissues (p < 0.05), but not for gastric and ovarian cancer (p < 0.05)." (PMID 36186486, 2022). "BTG3 expression was positively related to the survival rate of gastric and ovarian cancer patients (p < 0.05), but not for breast cancer (p < 0.05)." (PMID 36186486, 2022). "There appeared to be a negative relationship between BTG3 expression and the overall survival rate of patients with Luminal-B breast cancer (p < 0.05, data not shown)." (PMID 36186486, 2022).
gastric cancer (7 papers, 2015 to 2024). A primary or metastatic malignant neoplasm involving the stomach. "In addition, BTG3 mRNA expression was positively linked to the differentiation of gastric cancer, in line with our previous report about gastric cancer tissues." (PMID 36186486, 2022). "Therefore, we hypothesize that differential BTG3 expression underlies the molecular mechanisms of both gastric carcinomas, which is also supported by ALP results." (PMID 25904053, 2015). "BTG3 methylation was lower in gastric cancer than in normal tissues (p < 0.05), and G1 than G3 carcinoma (p < 0.05) by UALCAN." (PMID 36186486, 2022). "We used Cho’s and Chen’s datasets to perform bioinformatics analysis, and found that BTG3 expression was higher in gastric cancer than in normal tissues, even stratified into intestinal-, diffuse-, and mixed-type carcinomas (p < 0.05)." (PMID 36186486, 2022). "In breast and gastric cancer, the correlation between BTG3 mRNA and aggressive behaviors was the opposite to that between BTG3 methylation and them." (PMID 36186486, 2022). "Previous studies have shown that upregulation of BTG3 suppresses the migration and invasion capabilities of gastric cancer, and downregulation of BTG3 shows the opposite effect." (PMID 29270670, 2018). "The down-regulated BTG3 expression was attributable to its promoter methylation in breast, lung, prostate or renal, hepatocellular, and gastric cancer tissues or cells." (PMID 28407690, 2017). "BTG3 expression was restored after 5-aza-2′-deoxycytidine or MG132 treatment in gastric cancer cells." (PMID 25904053, 2015). "Among 38 cases of frozen gastric samples, 29kDa bands of BTG3 were weaker in gastric cancer than matched mucosa (p < 0.05)." (PMID 25904053, 2015). "There was a positive correlation between BTG3 expression and venous invasion of gastric cancer (p < 0.05)." (PMID 25904053, 2015). "Here, BTG3 overexpression was found to in vivo and vitro induce the autophagy of gastric cancer cells with Beclin 1 overexpression, indicating that BTG3-mediated autophagy was dependent on beclin-1 expression." (PMID 25904053, 2015). "BTG3 expression was decreased in gastric cancer in comparison to the adjacent mucosa (p < 0.05), and positively correlated with venous invasion and dedifferentiation of cancer (p < 0.05)." (PMID 25904053, 2015). "Based on the findings of immunohistochemistry and Western blot, BTG3 expression was reduced in gastric cancer, compared with adjacent mucosa, indicating that down- regulated BTG3 expression enhanced the malignant transformation of gastric epithelial cells." (PMID 25904053, 2015). "BTG3 overexpression in vitro decreased migration, invasion and lamellipodia formation of gastric cancer cells with a down-regulated expression of MMP-9 and VEGF." (PMID 25904053, 2015). "Statistically, BTG3 expression was decreased in gastric cancer in comparison to the adjacent mucosa (p < 0.05)." (PMID 25904053, 2015). "BTG3 overexpression induces S/G2 arrest in gastric cancer cells." (PMID 29270670, 2018). "BTG3 is reportedly a candidate tumor suppressor, as it inhibits cell proliferation and migration, and regulates cell cycle progression in several tumors, such as gastric cancer and esophageal adenocarcinoma." (PMID 29270670, 2018). "Our group also demonstrated that BTG3 overexpression inhibited proliferation, migration, invasion and tumor growth, induced S/G2 arrest, differentiation, autophagy, apoptosis and chemosensitivity of gastric cancer cells." (PMID 28407690, 2017). "BTG3 overexpression might reverse the aggressive phenotypes and be employed as a potential target for gene therapy of gastric cancer." (PMID 25904053, 2015). "BTG3 mRNA was detectable in gastric cancer and epithelial cells, except HGC-27." (PMID 25904053, 2015). "MG132- induced BTG3 overexpression indicated that BTG3 hypoexpression might be due to its ubiquitin- proteasome degradation in gastric cancer." (PMID 25904053, 2015).
gastric cancer (continued). "In the present study, we also found that BTG3 overexpression might ameliorate β-catenin, promote p38 and NF-κB expression in gastric cancer cells, indicating that BTG3 might target these signal pathways." (PMID 25904053, 2015). "Moreover, we demonstrated that BTG3 enhanced the sensitivity of gastric cancer cells to chemotherapeutic agents, which was positively associated with their apoptotic induction and the down-regulated expression of drug resistance genes (GRP78 and TOP2)." (PMID 25904053, 2015). "Finally, the in vitro and in vivo effects of BTG3 overexpression on aggressive behaviors of gastric cancer cells were determined in nude mice." (PMID 25904053, 2015). "BTG3 overexpression might reverse the aggressive phenotypes of gastric cancer cells and be employed as a target molecule for gene therapy." (PMID 25904053, 2015). "Moreover, BTG3 expression may predict survival and prognosis in patients with gastric cancer and ovarian carcinoma." (PMID 29270670, 2018). "To clarify the roles of BTG3 in gastric carcinogenesis, we investigated the effects of BTG3 overexpression on cell proliferation, apoptosis, autophagy, senescence, invasion, migration and lamellipodia formation of gastric cancer cells and screened the expression of the phenotype- related genes." (PMID 25904053, 2015). "In the present study, BTG3 overexpression in vitro inhibited proliferation, induced apoptosis and senescence, and S/G2 arrest of gastric cancer cells, and in vivo suppressed the growth of gastric cancer cells by inhibiting proliferation, inducing apoptosis and autophagy." (PMID 25904053, 2015). "In contrast, BTG3 positivity was not linked to age, sex, depth of invasion, lymphatic invasion, lymph node metastasis, distant metastasis or TNM staging of gastric cancer (p > 0.05)." (PMID 25904053, 2015). "In addition, we examined the expression of BTG3 mRNA and protein in gastric cancer, non-cancerous mucosa and cancer cell lines, and compared them with clinicopathological parameters of cancer." (PMID 25904053, 2015).